GLYATL1 (glycine-N-acyltransferase like 1)
Description:
Acyltransferase which transfers an acyl group to the N-terminus of glutamine. Can use phenylacetyl-CoA as an acyl donor.
Synonyms: GNAT; MGC15397; FLJ34646; GATF-C
Tractability: PROTAC: its protein half-life has been measured.
Gene: Protein-coding gene on chromosome 11 (58,905,398 to 59,043,527, forward strand). Ensembl gene ENSG00000166840.
Subcellular location (Human Protein Atlas): Golgi apparatus; Cytosol
Pathways (Reactome):
Metabolism: Conjugation of benzoate with glycine; Conjugation of carboxylic acids; Conjugation of salicylate with glycine
Drug ADME: Aspirin ADME
Gene Ontology:
Molecular function: glutamine N-acyltransferase activity; glycine N-acyltransferase activity
Biological process: glutamine metabolic process
Cellular component: mitochondrion
Genetic constraint (gnomAD): Loss-of-function variants: 15 observed, 21.63 expected, observed/expected ratio (o/e) 0.69, 90% interval 0.46 to 1.07. The upper end of that interval is the gene's LOEUF score, 1.07, which puts it in group 4 of 6, group 1 being the genes least tolerant of losing a copy. Missense variants: 377 observed, 382.76 expected, observed/expected ratio (o/e) 0.98, 90% interval 0.9 to 1.07. Synonymous variants: 150 observed, 138.83 expected, observed/expected ratio (o/e) 1.08, 90% interval 0.94 to 1.24.
Homologues: Orthologues: chimpanzee GLYATL1 (94% identical), tropical clawed frog glyatl2 (30% identical), zebrafish si:dkey-76k16.6 (25% identical), zebrafish si:ch73-106k19.2 (23% identical), Caenorhabditis elegans T10B10.4 (19% identical), zebrafish si:dkey-76k16.5 (19% identical), Caenorhabditis elegans ZK185.3 (18% identical), Caenorhabditis elegans F43H9.4 (11% identical). Paralogues in human: GLYATL1B (82% identical), GLYATL2 (49% identical), GLYAT (38% identical), GLYATL3 (31% identical).
Diseases named in the same sentence as GLYATL1 in open-access papers:
GLYATL1 is named in the same sentence as 16 diseases in open-access papers, as found by Europe PMC text mining. Sharing a sentence is not in itself a finding about the gene and the disease. The quoted sentences say what the papers report.
prostate carcinoma (5 papers, 2013 to 2022). A carcinoma that arises from epithelial cells of the prostate gland. "This study also demonstrated that GLYATL1 may be associated with the grade of prostate cancer since the expression of GLYATL1 was significantly high in low-grade tumors." (PMID 33868991, 2021). "Using public published big data, we found that the expression of succinylation-related gene Glycine-N-acyltransferase-like 1 (GLYATL1) and prostate cancer-related gene (AR) in 498 PCa tissues were significantly higher than that in non-cancer tissues." (PMID 36387072, 2022). "Silencing of KDM2A, FAM83H and GLYATL1 significantly inhibited the clonogenicity of prostate cancer cells in vitro." (PMID 27792127, 2016). "The functional version of this pseudogene, GLYATL1, has been found to be differentially expressed in a cell line-based prostate cancer progression model." (PMID 23826159, 2013). "GLYATL1 was also reported to overexpress in primary prostate cancer." (PMID 36171187, 2022).
hepatocellular carcinoma (4 papers, 2013 to 2024). A malignant tumor that arises from hepatocytes. "However, loss of GLYATL-1 expression was significantly associated with higher Gleason scores in prostatic adenocarcinoma, with shorter overall survival in hepatocellular carcinoma patients." (PMID 36672708, 2023).
breast carcinoma (3 papers, 2022 to 2026). "More importantly, GEPIA confirmed that higher GLYATL1 mRNA is associated with poor overall survival in breast cancer patients." (PMID 35933447, 2022). "Thus, we selected RANBP3L and GLYATL-1 to compare the expression of their encoded proteins in breast carcinoma tissue samples and determine the relationship between the expression of the proteins and the age of breast cancer patients." (PMID 36672708, 2023). "Survival analyses in the present study revealed that loss of RANBP3L, GLYATL-1, ESR1, and SFXN2 was significantly related to lower RFS in breast cancer (p-value < 0.012, 1.1 × 10−6, 1 × 10−16, and 1.3 × 10−10, respectively)." (PMID 36672708, 2023). "Normal breast ducts showed a higher expression of GLYATL-1 compared to breast carcinoma in situ and invasive breast carcinoma tissues." (PMID 36672708, 2023). "For GLYATL-1, only one published report described the protein expression in clinical breast cancer samples." (PMID 36672708, 2023). "The TCGA data showed that young-age breast cancer patients have a lower level of expression of RANBP3L, GLYATL-1, and ESR1, whereas ACVR2A, SERPINE2, and PCDHGB7 have higher expression in young-age breast cancer patients compared to old age patients." (PMID 36672708, 2023).
breast invasive carcinoma (2 papers, 2022 to 2023). "Consistent with our fly data, in the UALCAN cancer database containing TCGA data, the expression of GLYATL1 and GADD45G are elevated in breast invasive carcinoma, compared with normal tissues." (PMID 35933447, 2022).
clear cell renal carcinoma (2 papers, 2022 to 2024). A malignant epithelial neoplasm of the kidney characterized by the presence of lipid-containing clear cells within a vascular network. "Studies suggest that the high expression of GLYATL1 is related to the improvement of overall survival of renal clear cell carcinoma, liver cancer, bladder cancer, cervical cancer, lung cancer, ovarian cancer and other tumors." (PMID 36387072, 2022).
liver cancer (2 papers, 2022 to 2023). An epithelial or non-epithelial malignant neoplasm that arises from the liver. "Pseudogene PLGLA can inhibit the proliferation and division of liver cancer cells by regulating the miR-324-3p/GLYATL1 axis." (PMID 36941564, 2023).
breast tumors (1 paper, 2023). "Protein expression analysis results revealed a strong association between the loss of GLYATL-1 expression and breast tumors with positive lymph node status (p-value 0.005)." (PMID 36672708, 2023).
metastatic prostate carcinoma (1 paper, 2021). A carcinoma that arises from the prostate gland and has spread to other anatomic sites. "In a previous study, the expression of GLYATL1 was higher in localized prostate cancers than in benign prostatic tissue and metastatic prostate cancer." (PMID 33868991, 2021).
tumor (6 papers, 2019 to 2024). "Of the top 20 differentially expressed proteins identified in tumour samples, four (MDH2, FASN, EPCAM, and HSD17B10) are targetable by FDA-approved drugs, whereas two (AMACR and GLYATL1) are potentially targetable and are of potential interest for future research." (PMID 38052461, 2024).
GLYATL1 also shares sentences with these, for which no sentence is quoted: cancer (2 papers); bladder cancer (1); breast carcinoma in situ (1); cervical cancer (1); lung carcinoma (1); ovarian carcinoma (1); prostatic adenocarcinoma (1).